KRAS (KRas proto-oncogene, GTPase)
Diseases named in the same sentence as KRAS in open-access papers (continued):
Sharing a sentence is not in itself a finding about the gene and the disease.
lung adenocarcinoma (continued). "As a paradigmatic example, a recent study exploiting in vivo CRISPR‐Cas9 screening identified the COX‐2/PGE2 axis as a major mechanism shaping the TME in KRAS‐induced lung adenocarcinoma, since oncogenic KRAS triggered COX‐2 overexpression in cancer cells to alter tumor immunity." (PMID 39973474, 2025). "Studies have shown that some patients with LCCA may harbor molecular mutations, including EGFR, KRAS, and ALK gene rearrangements, which are more commonly found in NSCLC, particularly in lung adenocarcinoma." (PMID 40927518, 2025). "Considering the environment of KRAS-promoted lung adenocarcinoma, CUL4B exerts its tumor-suppressing capabilities via intricate epigenetic processes that encompass coordinated interplay with HDACs, ultimately inhibiting the transcription of C-X-C motif chemokine ligand 2 (CXCL2)." (PMID 40230836, 2025). "Conversely, KRAS mutations are present in only approximately 30% of lung adenocarcinomas, while EGFR mutations occur in 10-15% of non-Asian and up to 50% of Asian patients with non-small cell lung cancer (NSCLC)." (PMID 40656425, 2025). "Importantly, administration of HG106 to various preclinical mouse models of KRAS-mutant lung adenocarcinoma resulted in significant tumor suppression and prolonged survival." (PMID 39569390, 2025). "It would also be of interest to see whether these findings extend to other KRAS mutants such as KRASG12C, which can also be targeted to produce an antitumor immune response, or to other KRAS‐mutated cancer contexts such as lung adenocarcinoma." (PMID 39592415, 2025). "Oncogenic KRAS regulates myeloid cells in the microenvironment of lung adenocarcinoma." (PMID 39782689, 2025). "The prominent expression of CCR2 in specific clinicopathologic/molecular subgroups of lung adenocarcinomas harboring oncogenic mutations in EGFR and KRAS, as well as in CRCs with microsatellite instability–high status further support the potential for refined patient selection." (PMID 39918395, 2025). "In this study, we confirm the frequencies of somatic mutations in these genes in the Mexican population, with 24% for EGFR and 16% for KRAS, compared to 20% and 10%, respectively in the Carrot-Zhang recent study that included Mexican patients with lung adenocarcinoma." (PMID 40430005, 2025). "Furthermore, our findings indicate that lung adenocarcinoma patients with a history of alcohol consumption have a lower rate of EGFR mutations and a higher rate of KRAS mutations." (PMID 39926430, 2025). "The incidence of KRAS is 14% in lung adenocarcinoma and 0.5–4% in lung squamous carcinoma." (PMID 38499647, 2024). "Another recent study reported that while STK11 mutation decreased survival probability in stage I lung adenocarcinoma, KRAS mutation showed no significant impact." (PMID 38884086, 2024). "RANKL is a negative prognostic indicator in patients with advanced KRAS‐mutated lung adenocarcinoma." (PMID 38549499, 2024).
lung adenocarcinoma (continued). "LKB1 loss was associated with STING loss irrespective of KRAS status both overall and in lung adenocarcinomas (LUACs) and, importantly, also in the metastatic setting." (PMID 38791897, 2024). "However, UHRF1 was also a proto-oncogene that overexpressed in several tumor tissues and high UHRF1 expression is a marker of poor prognosis in human KRAS mutant lung adenocarcinoma, while the exact role of UHRF1 in tumorigenesis remains elusive." (PMID 39341501, 2024). "Finally, we aimed to validate our observations using a distinct and more physiologically relevant murine model of KRAS-driven lung adenocarcinoma induced by endogenous expression of oncogenic KrasG12V." (PMID 39587064, 2024). "In this study, we selected a panel of lung adenocarcinoma cell lines harboring major mutations commonly found in LUAD tumors, more specifically mutations of EGFR (H1975), KRAS (PF139) and BRAF (PF901) oncoproteins, furthermore, we also included one cell line with no known driver mutations (H838)." (PMID 39227650, 2024). "We first investigated sotorasib, which is already approved for clinical treatment of KRAS-G12C lung adenocarcinoma, in combination with tipifarnib, an FTi that was recently granted Breakthrough Therapy Designation for treatment of HRAS mutant head and neck squamous cell carcinoma." (PMID 38278976, 2024). "Additional genes were identified using RNA-seq data from KRASG12C-mutant lung adenocarcinoma cell lines (H358 and H23) treated with a KRAS inhibitor and immortalized type II pneumocytes expressing an ER-KRASG12V fusion protein, which can be readily activated by administration of 4-hydroxytamoxifen." (PMID 38635884, 2024). "The most frequent KRAS mutation is KRASG12C, present in 13% of lung adenocarcinomas." (PMID 39301544, 2024). "Given the central role of Ferredoxin 1 as a signaling mediator in lung adenocarcinoma tumorigenesis, it is plausible that it may also contribute to KRAS G12C resistance." (PMID 38802900, 2024). "In lung adenocarcinoma, it has been observed the existence of differential transcript expression for certain genes, such as the KRAS and the CD274 genes for which the expression levels of a number of their splicing isoforms appeared to be associated with disease initiation and progression." (PMID 38059347, 2024). "Lung adenocarcinoma may harbor both activating and resistance mutations of the EGFR gene, and further, mutations of KRAS and BRAF oncogenes." (PMID 38953007, 2024). "Moreover, DUSP6 levels and ERK activity were recently reported to be under translational control in KRAS-mutant lung adenocarcinomas." (PMID 39436655, 2024). "Methylation of MEN1 is regulated by KRAS in lung adenocarcinoma, so it is possible that NRAS, the second most commonly mutated driver gene in melanoma, may similarly be responsible for the increased MEN1 promoter methylation observed in melanoma." (PMID 39336822, 2024). "In addition, our in silico analysis found a significant inverse correlation between HRAS and KRAS dependency in KRAS-G12C mutant lung adenocarcinoma suggesting that these two proteins can play a compensatory role in tumor growth." (PMID 38278976, 2024).
lung adenocarcinoma (continued). "Using this network, the authors constructed a CRISPR double-knockout library of RAS interactor genes and identified a synthetic lethal interaction of Rap1 GTPase-GDP dissociation stimulator 1 (RAP1GDS1) with ras homolog family member A (RHOA) in KRAS-mutant lung adenocarcinoma." (PMID 38275900, 2024). "Patients with KRAS-mutant NSCLC had a poor prognosis, and KRASG12C mutation with a poorer prognosis compared with other KRAS mutations accounted for 42% of KRAS-mutant lung adenocarcinoma." (PMID 38347129, 2024). "mTORC1 is hyperactive in LKB1/KRAS mutant lung adenocarcinoma cancer cells and, thus, targeting this pathway by mTOR inhibitors might represent an effective way of treating lung adenocarcinoma." (PMID 37190124, 2023). "We set out to investigate whether KRAS mutations could lead to an impaired innate immune response against tumors in 18 patients with lung adenocarcinoma (12 harbored WT KRAS [KRASWT] and 6 had KRAS mutations)." (PMID 36413402, 2023). "Unspecified KRAS mutational status was already known to have no prognostic impact on OS in patients with stage IV lung adenocarcinoma." (PMID 37674812, 2023). "This study investigated the association of contrast-enhanced Computed Tomography (CT) radiomic features of lung adenocarcinoma lesions, alone or integrated with clinical parameters, with tumor mutational status (EGFR, KRAS, ALK alterations) and Overall Survival (OS)." (PMID 37760521, 2023). "Interestingly, in addition to the AMPK-mTOR signaling pathway, SIRT3/ HIF-1α was significantly upregulated in KRAS mutant human lung adenocarcinoma lines (H460, A549, and H358)." (PMID 37190124, 2023). "Tumor heterogeneity across patients is a plausible explanation for this observation: although there are certainly frequently mutated driver genes in lung adenocarcinoma, such as EGFR, KRAS or STK11, only a minority of patients’ tumor is found positive for each of these mutations." (PMID 37938580, 2023). "Interestingly, in a KRAS-driven mouse model of lung adenocarcinoma combinatorial therapy with NVP-BEZ235 and ARRY-142886, a MEK inhibitor resulted in a larger reduction of tumor volume compared with NVP-BEZ235 alone." (PMID 37154160, 2023). "Interestingly, somatic mutations in NLRP3 together with 10 other genes including KEAP1, KRAS, and STK11 were reported to define a molecular signature associated with a subtype of NSCLC, the lung adenocarcinoma (LUAD)." (PMID 36746533, 2023). "The first example is MYC in KRAS-driven lung adenocarcinoma (LUAD)." (PMID 37142594, 2023). "The first cohort was a commercial tissue microarray containing 157 pairs of lung adenocarcinoma and normal adjacent tissue samples, which lacked KRAS mutation information." (PMID 36413402, 2023). "Similar results were reported in a study using single-center data from the United States, in which the median OS from the date of diagnosis of metastatic disease in patients with KRAS-mutant lung adenocarcinomas was 13 months in de novo patients and 18 months in recurrent patients (HR, 1.41)." (PMID 37248452, 2023). "Furthermore, 54 DEGs were found to be implicated in various progression stages of lung adenocarcinoma, while 41 and 46 DEGs were found to be different according to the EGFR or KRAS mutation status of the tumor, respectively." (PMID 36832225, 2023). "That has two reasons: first, our predictive model showed better performance without SMOTE, and second, it was reported that the KRAS mutation rate in lung adenocarcinoma is about 26.1%." (PMID 37509345, 2023).
lung adenocarcinoma (continued). "Despite the proportion of tumors harboring EGFR, ALK, or KRAS alterations being consistent with the frequency reported in lung adenocarcinoma, the reduced subgroup size, especially for ALK-positive cases, might have limited the strength of the models." (PMID 37760521, 2023). "Overall, our findings could provide novel therapeutic strategies to target KRAS-activated lung adenocarcinomas." (PMID 37882674, 2023). "CD47 and p-STAT3 protein levels were consistently upregulated, and miR-34a was downregulated in the lung adenocarcinoma samples compared with the paired normal controls, regardless of KRAS mutation status." (PMID 36413402, 2023). "Notch inhibition and RepSox treatment may be developed as therapeutic options for KRAS-mutant lung adenocarcinomas." (PMID 37882674, 2023). "Recent studies have highlighted kinase-independent roles of RAF1 in KRAS mutant lung adenocarcinoma that could either be anti-apoptotic or pro-proliferative." (PMID 37020037, 2023). "Moreover, while high p-AKT expression was positively correlated with poor overall survival in patients with lung adenocarcinoma, coordinated activation of KRAS (p-AKThi) and CD47 further increased the probability of a poor prognosis (HR, 1.81 vs. 1.46)." (PMID 36413402, 2023). "In contrast to our study, none of these studies, which focus on patients with lung adenocarcinoma have incorporated feature selection models and machine learning algorithms for predicting the mutational status of KRAS." (PMID 37508774, 2023). "For lung adenocarcinoma, the predominant amino acid substitution is G12C in KRAS." (PMID 37662925, 2023). "In this work, we first propose a radiogenomic workflow to characterize lung adenocarcinoma cases with respect to KRAS and EGFR mutational status using radiomic features extracted from the computed tomography (CT) images of patients affected by lung adenocarcinoma." (PMID 37508774, 2023). "Therefore, the MASE‐CE assay for detecting KRAS, NRAS, BRAF mutations and MSI status can also be applied to patients with other cancers, including pancreatic and lung adenocarcinomas." (PMID 36583506, 2023). "Our findings could provide new therapeutic strategies to target KRAS-activated lung adenocarcinomas." (PMID 37882674, 2023). "Identification of progenitor like tumor-initiating cells in KRAS-mutant lung adenocarcinoma may allow development of novel targeted therapeutics." (PMID 37882674, 2023). "In a transgenic mouse model of KRAS-driven lung adenocarcinoma, increased activity of the Myc transcription factor that regulates cholesterol homeostasis and cell growth led to an imbalance between cholesterol influx and efflux in tumors and accumulation of CE in lipid droplets." (PMID 37762567, 2023). "Thirty lung adenocarcinoma samples were confirmed to be KRAS-mutant and seventy were WT." (PMID 36413402, 2023). "In KRAS-mutant lung adenocarcinomas, significant activation of NRF1 targets was associated with worse prognosis, consistent with NRF1’s role as a regulator of the proteasome pathway, a key dependency in KRAS-mutant cancers." (PMID 36950380, 2023). "ZNF24 and SLC7A5 expression were significantly increased in KRAS mutant lung adenocarcinoma." (PMID 36505791, 2022). "KRAS mutations have been traditionally considered a negative prognostic factor in patients with lung adenocarcinoma, currently representing the biggest challenge for the modern precision oncology." (PMID 35012520, 2022).
lung adenocarcinoma (continued). "Integrin β1 was expressed in all molecular subtypes of lung adenocarcinoma, though expression was lower in EGFR-mutated tumors (n = 17, mean 1.4 ± SD 0.7) relative to KRAS-mutated tumors (n = 40, mean 1.9 ± SD 0.8, P = 0.03) and all other tumors (n = 8, mean 2.1 ± SD 0.5, P = 0.04) (data not shown)." (PMID 35763345, 2022). "However, establishing clonal cell linesfrom these tumors enabled the generation of an immunogenic syngeneictransplantation model of KRAS-mutant lung adenocarcinoma that was sensitive toimmunotherapy." (PMID 35930804, 2022). "Oncogenic KRAS is a driver of multiple cancers in addition to lung adenocarcinoma, so our work raises the question of whether iRhom2 also has a role in these other cancers." (PMID 35971826, 2022). "Heterogeneous to the two most common subtypes of lung adenocarcinoma and squamous cell carcinoma in NSCLC, driver mutations, primarily KRAS and MET mutations, may be intrinsic drivers of the malignant features of PSC." (PMID 36341325, 2022). "Additionally, future studies should investigate more differences in the differentiation of KRAS-mutant lung adenocarcinoma between patients from the Arabian Gulf and others." (PMID 36004014, 2022). "According to the COSMIC database, G12C, G12V, G12D, and G12A mutations are the most common KRAS single-amino acid substitutions in lung adenocarcinoma (LUAD), unlike the squamous cell histotype in which KRAS mutations are rare (3%–5%)." (PMID 36452502, 2022). "Using this method, we discovered that RAS transcriptional activity predicted clinical outcome in lung adenocarcinoma and several other solid cancers, where KRAS mutation alone did not." (PMID 36163168, 2022). "Moreover, as increasing evidence shows that KRAS mutations correlate with unresponsiveness to EGFR inhibitors, we tested the biological activity of DSF-102 in a lung adenocarcinoma cell line, the A549 KRAS mutant cells." (PMID 35954311, 2022). "Notably, genetic depletion or pharmacological inhibition of SLC7A11 induces synthetic lethality in KRAS-mutant lung adenocarcinoma, highlighting SLC7A11 as a potential therapeutic target for RAS-driven tumors." (PMID 36552652, 2022). "Active CREB was found overexpressed in lung adenocarcinoma in dependence of mutant KRAS signaling." (PMID 36048281, 2022). "Our analysis shows that 84% of lung adenocarcinomas exhibit clear evidence of RAS pathway activation independent of KRAS mutation status." (PMID 36163168, 2022). "Similarly, in a screen of mutant KRAS lung adenocarcinoma cells, HG106 was found to specifically inhibit SLC7A11 function and decrease tumor burden in vivo via ROS induction and mitochondrial and endoplasmic reticulum dysfunction." (PMID 35280777, 2022). "Interestingly, in a murine model of KRAS-driven lung adenocarcinoma, it was demonstrated that myc plays a role in the modulation of cholesterol metabolism." (PMID 35159223, 2022). "Recent studies of TCGA data in EGFR-mut, KRAS-mut, and wild-type (no known driver mutations) (WT) lung adenocarcinomas, confirmed this prediction as few genes were found to be conserved even among subtypes that shared a common tissue of origin." (PMID 36092893, 2022). "With regard to KRAS mutations, corresponding to the largest subgroup of oncogenic lung adenocarcinoma, it has been shown that the co-occurrence of genomic alterations in the STK11 and KEAP1 genes leads to a worse outcome in KRAS-mutated patients treated with immunotherapy." (PMID 35454832, 2022). "Hence, we have demonstrated that RAS84 performed optimally in classifying KRAS mutant lung adenocarcinoma tumours as active for RAS-driven transcription." (PMID 36163168, 2022).